ATF3 (activating transcription factor 3)
Diseases named in the same sentence as ATF3 in open-access papers (continued):
Sharing a sentence is not in itself a finding about the gene and the disease.
infection (continued). "To test whether Tsc2 deletion in adult mice induces a pro-regenerative landscape in the DRG, we assessed cJun and Atf3 expression as well as macrophage density in uninjured DRG of control-AAV8 and Tsc2 KO-AAV8 mice 3.5 weeks post-infection." (PMID 31182472, 2019). "Therefore, it seems that IL-1β production through ATF3-mediated ROS inhibition is necessary to prevent the inhibition of primed NLRP3, as a sufficient amount of ROS was secreted during infection in the case of gram-positive bacteria." (PMID 30214444, 2018). "Consistent with cytokines, ATF3 KO BMDMs exhibited increased ROS production after infection with either gram-positive or gram-negative bacteria." (PMID 30214444, 2018). "Indeed, we observed better survival following infection and a lower incidence of intestinal barrier dysfunction in Myots>UAS-BskDN, ATF3-RNAi flies, than in controls expressing ATF3-RNAi alone." (PMID 28272390, 2017). "In this study, we demonstrate that the ATF3-Raw module buffers excessive activation of JNK signalling and thereby restrains epithelial cell death, a function that is essential for normal gut homeostasis and optimal survival following infection." (PMID 28272390, 2017). "In particular, ATF3, a transcriptional repressor modulating responses to infection, is upregulated early, possibly as part of a negative feedback loop." (PMID 24357630, 2014). "The negative feedback role of ATF3 for controlling cytokine toxicity provides an advantage as a model of infection with high clinical relevance." (PMID 21152039, 2010). "RNA-seq data from wild-type and ATF3 knockout A549 human lung adenocarcinoma cells either mock-infected or infected with ZIKV PRVABC59 at a moi of 10 PFU/cell and harvested at 24 hours post-infection have been deposited in Gene Expression Omnibus (GEO) at GSE233049." (PMID 39212382, 2024). "Additionally, VSVΔ51 infection did not upregulate IκBζ protein levels thus fully excluding the ATF3-IκBζ axis as a possible mediator of the biological effects observed with 4-OI on VSVΔ51." (PMID 38750019, 2024). "Furthermore, L. amazonensis infection did not alter ipsilateral ATF3 mRNA expression in DRG cells at the 30th day post-infection indicating no neuronal lesion in contrast with neuropathic pain conditions such as CCI of the sciatic nerve." (PMID 31138231, 2019). "Infection of the hepatocyte sub-line Huh7.5.1 with JFH1 (2a) induced an acute ER stress peaking at 2–5 days post-infection (dpi), concomitant with phosphorylation of IRE1, eIF2α, and JNK, XBP1 splicing, ATF6 cleavage and upregulation of GADD34, ERdj4, P58IPK, ATF3, ATF4, and CHOP." (PMID 24904547, 2014). "Thus, Atf3 may also play a role in the ability of non-chemotherapy related stressors to facilitate metastasis, such as infection, traumatic injury, and even incisional surgery." (PMID 30373101, 2018). "Next, we used RT-qPCR (quantitative PCR with reverse transcription) to determine whether ATF3 is induced in the Drosophila midgut by various stresses, including infection with the Gram-negative bacteria Pseudomonas entomophila, ingested paraquat (induces oxidative stress) and ageing." (PMID 28272390, 2017). "ATF3 mRNA expression in DRG was determined in control non-infected and bilaterally in infected mice at day 30 after the infection by RT-qPCR." (PMID 31138231, 2019). "Interestingly, SARS-CoV-2 also induced ATF3 and GADD34 throughout the course of infection but failed to significantly upregulate CHOP." (PMID 39861909, 2025).
bacterial infection (9 papers, 2015 to 2023). "Subsequently, the function of ATF3 was applied to the study of multiple bacterial infection responses." (PMID 35370996, 2022). "As a part of eIF2 signaling, induction of activating transcription factor 3 (ATF3) during intracellular bacterial infection enhances pathogen clearing." (PMID 29257110, 2017). "Conversely, overexpression of either ATF3 or Raw significantly reduced the ISC proliferation induced by bacterial infection." (PMID 28272390, 2017). "In this study, we show that ATF3 plays a central role in the regulation of apoptotic responses and tissue regeneration following bacterial infection." (PMID 28272390, 2017). "To assess the regulation of Raw expression by ATF3, we examined its expression after bacterial infection (P.e) or ageing in enterocytes of ATF3-RNAi or ATF3-overexpressing flies." (PMID 28272390, 2017). "DMI elicits NRF2 and ATF3 activation in response to bacterial infection, promoting host defense." (PMID 37261340, 2023). "ATF3 KO mice are sometimes more susceptible and sometimes more resistant to bacterial infections, regardless of Gram-negative or positive strain or the action of inflammatory cytokines." (PMID 35370996, 2022). "Interestingly, ATF3 upregulation was also found to mediate protection against Gram-positive bacteria by enhancing cytokine production during bacterial infection." (PMID 31781116, 2019). "We hypothesized that ATF3 has a protective role in the Drosophila intestine in response to bacterial infection." (PMID 28272390, 2017). "Moreover, Nrf2 induces the expression of the activating transcription factor 3 (ATF3) in Mø, an IL-6 repressor that is protective against LPS but highly deleterious against bacterial infection." (PMID 26551709, 2015). "In myeloid cells, Atf3 becomes activated upon TLR stimulation, IFN stimulation or bacterial infection and either represses or induces cytokine production depending on the study design." (PMID 35396971, 2022).
cardiovascular disease (7 papers, 2021 to 2026). "ATF3 dysfunction is associated with several pathophysiological responses, including inflammation, apoptosis, oxidative stress and endoplasmic reticulum stress, as well as diseases such as cardiovascular diseases." (PMID 39731276, 2025). "Repurposing TZ to stabilize ATF3 offers a translatable approach to combat ageing-driven cardiovascular disease." (PMID 40641410, 2025). "The findings of this study provide novel insights into the role of ATF3 in cardiovascular disease progression." (PMID 41453996, 2025).
metabolic disorders (6 papers, 2018 to 2025). "However, little is known about the physiological functioning of ATF3 in hepatic glucolipid metabolism and metabolic disease or the underlying mechanisms." (PMID 36472556, 2023). "Given that the liver is a major site of glucolipid metabolism in the body, targeting hepatic ATF3 may represent a promising approach for the treatment of metabolic diseases caused by hepatic metabolic dysfunction." (PMID 36472556, 2023). "Taken together, these observations indicate that hepatocyte ATF3 plays critical roles in modulating glucolipid metabolism and protecting against metabolic disorders." (PMID 36472556, 2023). "Here, we briefly review the recent discoveries regarding the roles of ATF3 in glucose and lipid metabolism and metabolic diseases." (PMID 36472556, 2023). "In addition, adipocyte ATF3 can also influence glucolipid metabolism-related metabolic disorders by controlling adiponectin expression and secretion." (PMID 36472556, 2023). "Therefore, ATF3 is a key transcription factor that modulates glucolipid metabolism and related metabolic diseases by controlling a metabolic and inflammatory network through specific organs and cell types and inter-organ crosstalk." (PMID 36472556, 2023). "Thus, modulation of ATF3 activity holds the potential to improve glucolipid metabolic disorders and related metabolic diseases." (PMID 36472556, 2023). "The beneficial effect of ST32da in ameliorating the metabolic disorder and in reducing the depot weight of iWAT, eWAT, mWAT, rWAT, and BAT was lost in these HFD-fed ATF3−/− mice." (PMID 31667363, 2019).
myopathy (5 papers, 2014 to 2024). A disease of the muscle in which the muscle fibers do not function properly. "PGC-1β upregulates apoptosis and/or autophagy-related TFs, such as Atf3 and Stat3, subsequently triggering myopathy." (PMID 35812340, 2022). "Concurrently, PGC1β up-regulates apoptosis and/or autophagy transcriptional factors such as E2f1, Atf3, Stat1, and Stat3, which may be facilitating myopathy." (PMID 28860475, 2017). "Furthermore, the downregulation of ATF3 might reflect an adaptive response to stabilize oxidative stress, apoptosis, and inflammation during the development of the myopathy, thereby aiding in the repair of muscle tissue damage." (PMID 39199913, 2024). "Whether ATF3 or ATF5 plays a role in myopathy is also not understood, though ATF5 loss did not affect the response of HeLa cells to mitochondrial dysfunction." (PMID 35531957, 2022).
neurodegenerative disease (5 papers, 2022 to 2025). A disorder of the central nervous system characterized by gradual and progressive loss of neural tissue and neurologic function. "Specific TFs activated with an NES > 0 (female PD patients), such as ATF3, BCL6, or PCGF2, have been associated with neurodegenerative diseases or cognitive disabilities." (PMID 36414996, 2022). "Of the transcription factors altered in female PD patients, ATF3, BCL6, and PCGF2 have been previously associated with neurodegenerative diseases or cognitive disabilities." (PMID 36414996, 2022). "ATF3 can also promote the progression of neurodegenerative diseases." (PMID 35592698, 2022). "Therefore, the finding of a potential suppression of SNAP25, with or without ATF3 getting involved, in SOD1-mutant ALS patients might indeed be of importance and point to a general role in neurodegenerative diseases." (PMID 37491426, 2023).
cardiac disease (4 papers, 2013 to 2020). "However, following sustained stress,ATF3 expression is detrimental and can contribute to heart disease development." (PMID 23874609, 2013). "Among these, cardiac disease is a model that we have been using to investigate JDP2 and ATF3." (PMID 30818334, 2019).
peripheral neuropathy (4 papers, 2017 to 2025). A disorder affecting the peripheral nervous system. "Paclitaxel-induced peripheral neuropathy in vivo stimulated the expression of activating transcription factor 3 (ATF3; a marker of cellular injury) in myelinating SCs in the sciatic nerve." (PMID 40940747, 2025). "We observed downregulation of histone genes by 5-FU (that significantly correlates with improved survival in CRC patients) and upregulation of FOS and ATF3 by oxaliplatin (which may contribute to peripheral neuropathy)." (PMID 34611476, 2021). "These include downregulation of histone genes by 5-FU (that significantly correlates with improved survival in CRC patients) and upregulation of FOS and ATF3 by oxaliplatin (which may contribute to peripheral neuropathy)." (PMID 34611476, 2021). "As is typical of CIPN, PTX treatment also produced marked peripheral neuropathy evidenced by prolonged changes in the sensitivity to mechanical, cold and heat stimuli, by prolonged degeneration of IENFs, and by increased expression of the neuronal injury marker, ATF3, in the DRG." (PMID 29125463, 2017).
cerebral artery (3 papers, 2022 to 2025). "The participation of activating transcription factor 3 (ATF3) in transient middle cerebral artery occlusion and reperfusion injury has been reported." (PMID 35263513, 2022).
proliferative retinopathy (2 papers, 2012 to 2025). "Moreover, ATF3 deletion in a model of oxygen-induced retinopathy inhibited retinal vascular repair but not pathological neovascularization." (PMID 39790557, 2025).
brain disorder (1 paper, 2023). A disease affecting the brain or part of the brain. "Challenges ahead will be to investigate the roles and function of TGM1, TGM2, ATF3, RCN3, ORAI1, and ITPR3 in TBI as well as TBI-induced secondary brain disorders." (PMID 37645012, 2023).
nervous system disease (1 paper, 2025). "Among these, 31 were up-regulated and 75 were down-regulated in NP rats compared with sham rats, such as nervous system disease-related genes Zeb1, Atf3, Vip, and Aurkb." (PMID 40485981, 2025).
ATF3 also shares sentences with these, for which no sentence is quoted: immune disorders (4 papers); nonalcoholic fatty liver disease (4); acute lung injury (3); fibrosis (3); Pain (3); sarcoma (3); chronic periodontitis (2); Clear Cell Renal Cell Carcinoma (2); colon adenocarcinoma (2); diabetic cardiomyopathy (2); focal segmental glomerulosclerosis (2); head and neck cancer (2); hypertrophy (2); kidney disease (2); pterygium (2); radiculopathy (2); sarcopenia (2); tuberculosis (2); Type 1 diabetes (2); Ventricular hypertrophy (2); acute myocardial infarction (1); acute respiratory distress syndrome (1); alcoholic steatohepatitis (1); anaplastic thyroid cancer (1); aneurysm (1); Anxiety (1); aortic stenosis (1); bacterial sepsis (1); Benign Prostate Hyperplasia (1); bladder urothelial carcinoma (1).
A further 68 diseases each share a sentence with ATF3 in 1 paper.